PFKP (phosphofructokinase, platelet)
Diseases named in the same sentence as PFKP in open-access papers (continued):
Sharing a sentence is not in itself a finding about the gene and the disease.
tumor (continued). "The results indicated a significant deceleration in tumor proliferation following in vivo targeted PFKP knockdown by NPs-encapsulated siPFKP compared to the control groups of NPs(siNT) and Naked(siPFKP)." (PMID 39664584, 2024). "PFKP, targeted by hypoxia-inducible factor 1 alpha (HIF1a), has close relation with tumor aerobic glycolysis, tumor growth, immune evasion and reducing metabolic load under glucose starvation." (PMID 38977778, 2024). "This targeted delivery effectively suppresses PFKP expression in vivo, consequently impeding tumor growth." (PMID 39664584, 2024). "To confirm these findings, we downloaded the expression levels of PFKP from the GTEx database (for human normal tissues) and TCGA database (for human tumor tissues)." (PMID 37151384, 2023). "Herein, we demonstrated that higher expression of PFKP in tumor samples was generally found across cancers." (PMID 37833332, 2023). "To assess the significance of PFKP in immunotherapy, the most promising tumor treatment, we detected the correlation between PFKP and PD-L1." (PMID 37833332, 2023). "The expression levels of PFKP were significantly increased in tumor tissues compared to normal tissues, including breast, colon, lung, and stomach." (PMID 37151384, 2023). "Meanwhile, higher level of PFKP was found in tumor tissue compared with adjacent normal tissue in the TCGA LUAD dataset." (PMID 35641476, 2022). "What’s more, hypoxia-inducible factor-1α (HIF-1α) is a key transcriptional regulatory protein that regulates an arrangement of hypoxia-sensitive proteins expression, such as PKM2, HK2, PFKP, to preserve the survival of tissue in tumor microenvironment." (PMID 36536346, 2022). "HRD1 overexpression inhibited the tumor growth, whereas ectopic expression of PFKP reversed this inhibition." (PMID 33588886, 2021). "More importantly, restoration of PFKP expression abolished the tumor suppressive effects of HRD1 both in vitro and in vivo." (PMID 33588886, 2021). "We next examined the role of β-catenin regulation by PFKP Y64 phosphorylation in the EGFR activation-induced tumor cell proliferation." (PMID 32195176, 2020). "Depletion of PFKP largely inhibited tumor cell proliferation in U87/EGFRvIII cells, and this inhibition was alleviated by reconstituted expression of WT Flag-rPFKP, but not by rPFKP Y64F mutant." (PMID 32195176, 2020). "Further, dynamic suppression of PFKP restored the in vivo tumour-initiating and metastatic potential of cancer cells having a Snail-knockdown background." (PMID 28176759, 2017). "Using a TMA of stage I ccRCC tumor and normal-adjacent tissue, PFKP was increased 1.64-fold in tumor tissue (t-test, p < 0.001), and increased 3.63-fold in tumor (t-test, p < 0.001)." (PMID 27128972, 2016). "We found the key glycolytic enzyme-encoding gene PFKP that is located at the short arm of chromosome 10, overexpressed in <20% of the GBM tumor tissue samples but >20% of the normal brain samples." (PMID 24282503, 2013). "C1QBP and PFKP are critical cuproptosis-related genes in LUAD, with their high expression linked to poor prognosis and increased tumor progression; targeting these genes could offer potential therapeutic strategies for managing LUAD." (PMID 41041346, 2025). "High PFKP expression enhances glycolysis, supporting rapid tumor cell proliferation and invasion." (PMID 41041346, 2025). "The presence of PFKP in all four datasets highlights its significance in tumor metastasis and may have exciting roles in disease progression." (PMID 40821334, 2025). "qPCR validated the higher mRNA expression levels of C1QBP and PFKP in tumor tissues." (PMID 41041346, 2025). "Nanoparticles-mediated PFKP silencing can inhibit tumor growth in vivo." (PMID 39664584, 2024). "In contrast, PFKP overexpression promoted tumor growth in the xenograft model assay." (PMID 38982480, 2024). "Moreover, silencing PFKP collaborated with RT to restrain tumor cell survival, stimulated cGAS/STING signaling pathway and increased cell apoptosis." (PMID 38977778, 2024).
tumor (continued). "Additionally, our multiple models demonstrate that co-targeting PFKP and c-Myc triggers synergistic anti-tumor effects in HNSCC." (PMID 38982480, 2024). "Indeed, we found that targeting PFKP with siRNA or shRNA in combination with a c-Myc inhibitor had a potent anti-tumor effect in three preclinical tumor models, including the LIU-LSC-1 CDX, HNSCC PDO, and HNSCC PDX models, respectively." (PMID 38982480, 2024). "Further, NPs-mediated PFKP silencing inhibited tumor growth in vivo." (PMID 39664584, 2024). "Remarkably, the tumor tissues exhibited elevated PFKP expression levels." (PMID 38982480, 2024). "Additionally, knockdown of Serinc2 inhibited tumor growth and reduced the protein expression of c‐Myc, PFKP, LDHA, and PDK1 in vivo." (PMID 39417376, 2024). "Furthermore, analysis of our HNSCC tumor samples confirmed a positive correlation between PFKP and c-Myc expression." (PMID 38982480, 2024). "The genes PFKP, PFKM, and PGK1 were associated with oncogenes that could reinforce the Warburg effect and tumor progression." (PMID 39684297, 2024). "Moreover, an immunohistochemistry staining assay was used to investigate the expression of PFKP protein in each sample of mice tumor tissue." (PMID 38217030, 2024). "This suggests that overexpression of LDHA and PFKP could be an important factor not only for tumor progression but also for the development of metastases." (PMID 37326348, 2023). "Our data suggested that the glycolysis-related kinase PFKP was highly expressed across cancers and positively correlated with tumor immune cell infiltration and immune-related genes, suggesting that PFKP could be an important immunoregulation marker." (PMID 37833332, 2023). "Furthermore, to explore the relationship between PFKP and tumorigenesis/progression, the tumor stage relevance of PFKP was determined." (PMID 37833332, 2023). "GSEA data also indicated that PFKP could participate in tumor immune regulation because of its close connection with the inflammatory response and TNF-α signaling via NF-κB hallmarks." (PMID 37833332, 2023). "Furthermore, to clarify and summarize the function of PFKP across cancers, TCGA tumor samples were divided into two groups according to high or low expression of PFKP." (PMID 37833332, 2023). "In summary, PFKP may play an important role in immune system regulation across cancers as suggested by the strong correlation of PFKP with immune cells, tumor immune cell infiltration, and immune-related genes." (PMID 37833332, 2023). "In contrast, MAP2K7, CELSR3, and PFKP were overexpressed in tumor tissues." (PMID 36339718, 2022). "However, tumor sizes were comparable between groups injected with control shRNA-expressing and PFKP shRNA-expressing LN229 cells at an early stage." (PMID 36435833, 2022). "This study identifies PFKP as a critical factor in hypoxia/HIF-1α-induced NSCLC tumor cell proliferation, invasion, and metastasis that may represent a metabolic vulnerability in NSCLC tumors." (PMID 34367973, 2021). "Western blotting and immunohistochemistry analyses revealed that overexpression of PFKP could restore PFKP levels in the tumor tissues expressing HRD1." (PMID 33588886, 2021). "What’s more, PFKP was proven to be mainly regulated by the heterogeneity of substrates, and its abnormal expression or structural variation was also one of the critical reasons leading to reprogramming of tumor glycolysis." (PMID 32470015, 2020). "Therefore, our observations suggest a possibility that metabolic reprogramming towards PPP via suppression of PFKP can increase the tumour-initiating and metastatic potential of cancer cells by overcoming metabolic stress." (PMID 28176759, 2017). "Further, the overexpression of PFKP attenuated tumour-initiation and metastatic potential in vivo." (PMID 28176759, 2017). "Our findings show that PFKP suppression inhibits ccRCC tumor growth in vivo." (PMID 27049827, 2016). "We found that PFKP was consistently up-regulated in ccRCC tumor samples." (PMID 27049827, 2016).
tumor (continued). "However, significantly longer transcripts that are normally overexpressed, enriched in transcripts that are involved in glucose metabolism (including, e.g., the transcript of the human gene PFKP) and brain activity, are suppressed in the tumor." (PMID 24282503, 2013). "Importantly, Akt can directly phosphorylate PFKP at S386, which prevents the interaction of PFKP with E3 ligase TRIM21 and the subsequent TRIM21-mediated polyubiquitination and degradation of PFKP, resulting in increased PFKP expression, aerobic glycolysis, cell proliferation, and tumor growth." (PMID 40612109, 2025). "In addition to promoting glycolysis, emerging evidence also suggests that PFKP may influence tumor progression through other mechanisms." (PMID 38982480, 2024). "Finally, the combined inhibition of PFKP and c-Myc may yield synergistically anti-tumor effects on HNSCC progression." (PMID 38982480, 2024). "Finally, the functions of PFKP were mainly enriched in cell cycle operation and tumor metastasis." (PMID 37833332, 2023). "Furthermore, suppression of PFKP led to reduced ccRCC tumor growth in vivo." (PMID 27049827, 2016). "Mechanistically, we found that PITX1 transcriptionally activates Phosphofructokinase platelet (PFKP), a key glycolytic enzyme, thereby enhancing glycolytic flux to promote tumor growth and metastatic capacity." (PMID 42065039, 2026). "Molecular biology experiments on tumor tissues from 5 LUAD patients revealed higher expression of C1QBP and PFKP in tumors compared to adjacent tissues." (PMID 41041346, 2025). "We found the increased expression of PFKP, TPX2, UBE2S, ST6GALNAC4, ADAM15, G6PD, and KPNA2, but decreased expression of GOT2 in tumor samples compared to normal samples." (PMID 40307857, 2025). "KAT5 mediates PFKP acetylation, leading to its membrane translocation, subsequently activating PFK1 and increasing GLUT1 expression, thereby promoting glycolysis and tumour cell proliferation." (PMID 39778006, 2025). "Among the 7 HRGs included in the hypoxia risk score model constructed in this study, these 6 genes (LDHA, PGK1, PFKP, DCN, LOX, FBP1) have been extensively reported in previous studies for their roles in tumor hypoxia response and progression." (PMID 40464853, 2025). "PFKP was differentially expressed in other tumor types except for READ and was expressed higher in tumor tissues than in normal tissues." (PMID 38965505, 2024). "To further determine the role of PFKP on TNBC progression in vivo, we established xenograft tumor models in nude mice." (PMID 38217030, 2024). "Consistent with our CDX findings, co-treatment with PFKP siRNAs and 10,058-F4 more effectively suppressed PDX tumor growth compared to either treatment alone." (PMID 38982480, 2024). "The combination of PFKP siRNA and 10,058-F4 led to a stronger inhibitory effect on LIU-LSC-1 xenografts than either single agent alone, as shown by tumor volume and weight." (PMID 38982480, 2024). "By quantitative mass spectrometry analysis with anti-ACSL4 immunoprecipitates from lysates of HONE1 bulk tumor cells or TRCs, we identified kinases PCK2, PKM2 and PFKP, as well as phosphatase PPM1G, from the top 250 most enriched proteins in the precipitates." (PMID 38720107, 2024). "IHC staining showed that depletion of PFKP significantly reduced both Ki-67 (a marker of proliferation) and CD31 (an angiogenic marker) expression in tumor tissues." (PMID 38982480, 2024). "Downregulation of the expression levels of HK2, PFKP, and PDH, as well as the phosphorylation level of ERK1/2 was observed in both 2D and 3D cultures or tumor tissues in nude mouse xenograft models treated with the combination of two agents." (PMID 39770959, 2024).
tumor (continued). "Within the glycolysis pathway, genes such as HK2, PFKP, and PKM displayed elevated expression, thereby emerging as prospective targets warranting exploration for restraining tumor cell glycolytic activity." (PMID 38414015, 2024). "Genes in CDR signature had been reported to participate in tumor immunity process, in which LOXL2 and PFKP were apparently with high index in CDRSig." (PMID 38977778, 2024). "In our snATAC-seq data, we also observed motifs of HIF1A in the PFKP, ENO2, and HK1 open promoter regions that are more accessible in tumor cells, consistent with the previous reports of HIF1A regulating these genes." (PMID 36973268, 2023). "We observed that the expression levels of GLUT1 (SLC2A1) and the glycolytic rate-limiting enzymes HK2 and PFKP were increased in response to stress both in mRNA and protein levels in CRC cells and tumor tissues." (PMID 37151872, 2023). "Next, we examined the expression of key enzymes catalysing glycolysis such as PFKP, ENO1, PKM and LDHA in ccRCC tumours and the matched controls." (PMID 35672925, 2022). "Quantitative PCR, immunoblotting, and a colorimetric assay further confirmed the decreased expression and reduced enzyme activity of HK2, PFKP, and PKM2 in PyMT;Zeb1cKO tumor cells compared to PyMT cells." (PMID 35246504, 2022). "The results revealed that IMP4 silencing reduced the levels of GLUT1, HK2, PFKP, PKM2, and LDHA in LUAD cells and tumour tissues." (PMID 36317123, 2022). "The upregulated SLC2A1 (GLUT1) (T/TA = 9.49), HK2 (T/TA = 36.69), PFKP (T/TA = 15.97), PKM (T/TA = 4.08), and LDHA (T/TA = 8.58) suggested the increased of glucose utilization for lactate fermentation in ccRCC tumor vs. adjacent tissues." (PMID 35440542, 2022). "Consistently, many genes coding for key glycolytic enzymes such as GLUT1, HK2, PFKFB3, PFKP, and PKM2 were significantly upregulated in HCC192Low tumors compared to HCC192High tumors but showed negligible alteration in their non-tumor tissues." (PMID 33256802, 2020). "AKT binds to and phosphorylates the PFK1 platelet (PFKP) isoform and elevates PFKP expression in GBM, leading to cell proliferation, tumor growth, and poor prognosis." (PMID 31450721, 2019). "Nevertheless, poorly differentiated cell lines mimicked upregulated expression of genes (in tumours) such as CAV1, COL4A1, and novel candidates such as TSPAN5, TENM2, C15orf48, PLAU, AHNAK2, FAM129A, PLAU and platelet-specific phosphofructokinase (PFKP)." (PMID 30176945, 2018). "Overall, we demonstrated that WNT5A signaling (via a β-catenin-PFKP axis) reduces lactate production and lowers the expression of MCT1, a carrier mediating the uptake of lactate from the tumor microenvironment." (PMID 29069720, 2017). "In terms of therapy, these insights suggest that targeting metabolic pathways, such as inhibiting LDHA or PFKP to disrupt glycolysis, or using MTORC1 inhibitors like rapamycin, may alleviate tumor growth and invasion." (PMID 40464853, 2025). "Notably, G6PD was predominantly expressed in early and mid-stages, while KPNA2, PFKP, and TPX2 were upregulated in advanced tumor states." (PMID 40307857, 2025). "PFKP is a rate-limiting enzyme in glycolysis, regulating metabolic flux and influencing epithelial-mesenchymal transition (EMT) and autophagy, thereby enhancing tumor invasiveness." (PMID 40464853, 2025). "As a pivotal component of the cyclin D-CDK4/6-Rb signaling pathway, CDK6 directly phosphorylates PFKP at S679 and PKM2 at S37, thereby increasing pentose phosphate metabolism and serine metabolism in tumor cells, elevating intracellular NADPH levels, and promoting tumor cell growth." (PMID 39980052, 2025). "Finally, we validated the tissue expression and in vitro functions of two genes, C1QBP and PFKP, which were found to be involved in copper ion metabolism in LUAC and affect tumor cell proliferation and invasion capabilities." (PMID 41041346, 2025).
tumor (continued). "As no literature showed direct relation among PFKP, tumor immune environment and RS, we further validated its function in vivo and in vitro." (PMID 38977778, 2024). "To explore whether PFKP protein has a potential role in the progression of TNBC, we queried the Clinical Proteomic Tumor Analysis Consortium (CPTAC) datasets using the UALCAN website." (PMID 38217030, 2024). "First, we compared the mRNA expression of PFKP between nontumor and tumor samples across cancers (33 cancer types)." (PMID 37833332, 2023). "It has been reported that ZBTB7A also acts as a key transcription factor in tumor cells, is closely related to the transcriptional regulation of key glycolytic enzymes, and transcriptionally represses GLUT‐3, PFKP, and PKM2 expression, affecting tumor progression and patient prognosis." (PMID 37066523, 2023). "LDHA and PFKP expression levels were significantly higher in tumor tissues than in HCTs (FC = 4.3 for LDHA and FC = 27.2 for PFKP); interestingly, the expression levels of both proteins were even higher in CC metastases than in HCTs (FC = 10.4 and 42.7, respectively)." (PMID 37326348, 2023). "Interestingly, the rate-limiting enzyme-coding genes in the glycolysis pathway showed inconsistent expression pattern in tumor cells compared with normal: HK3 and PFKP were overexpressed, while PFKM was downregulated." (PMID 37553601, 2023). "Moreover, CoQ10 downregulates PFKP levels—a key enzyme governing glycolysis, which is overactivated in GBM and promotes tumor growth." (PMID 36319818, 2023). "Such reciprocal action between PFKP and VEGF signaling might contribute to their overexpression within a tumor mass." (PMID 36435833, 2022). "Our strong evidence highlights that the nonmetabolic function of PFKP can induce angiogenesis and that angiogenesis-independent role of VEGF can induce aerobic glycolysis and cancer proliferation, which are mediated by reciprocal regulation between PFKP and VEGF to promote GBM tumor growth." (PMID 36435833, 2022). "To validate up-regulation of PFKP at the transcriptional level in ccRCC, we compared PFKP mRNA levels in 19 ccRCC tumor and 19 adjacent non-malignant kidney tissue samples using quantitative PCR." (PMID 27049827, 2016). "First, promoter methylation of PFKP between tumor and nontumor tissues was assessed across cancers." (PMID 37833332, 2023). "Moreover, paired nontumor and tumor samples from TCGA also displayed a higher PFKP level in tumors." (PMID 37833332, 2023). "However, whether PFKP and VEGF are reciprocally regulated during GBM tumor growth remains unknown." (PMID 36435833, 2022). "We found that stem cell-like GBM tumor subpopulations possessed higher basal levels of glycolytic activity and increased expression of several glycolysis-related enzymes including, GLUT1/SLC2A1, PFKP, ALDOA, GAPDH, ENO1, PKM2, and LDH, compared to their non-stem-like counterparts." (PMID 37420311, 2023). "Lactate dehydrogenase A (LDHA) and phosphofructokinase P (PFKP) were found to be significantly correlated with progression-free survival (PFS) and OS in patients with CC, and the expression level of LDHA in recurrent tumours was significantly higher than that in nonrecurrent tumours." (PMID 33228592, 2020).